FXN (frataxin)
Diseases named in the same sentence as FXN in open-access papers (continued):
Sharing a sentence is not in itself a finding about the gene and the disease.
Ataxia (74 papers, 2006 to 2026). Ataxia refers to impaired coordination of voluntary muscle movement. "Many forms of spinocerebellar ataxia, which are among the most common hereditary ataxias, are caused by trinucleotide repeat expansions in several genes (FXN, ATXN1, ATXN2, ATXN3)." (PMID 41010014, 2025). "Friedreich’s Ataxia (FA) is the most common form of human ataxia and arises from insufficient production of the frataxin (FXN) protein, typically caused by a triplet expansion in the nuclear FXN gene." (PMID 39684857, 2024). "During his life, the patient underwent extensive targeted testing for known genes associated with ataxia and spasticity (spastic paraplegias 3A, 4, and 7; spinocerebellar ataxias 1, 2, 3, 6, 7, and 14; FXN‐, APTX‐, SETX‐, PLP1‐, and LCFA‐related disorders)." (PMID 34753215, 2022). "It is unclear why the hypomorphic recessive alleles of FXN are specifically damaging the posterior root ganglia, the dorsal spinal columns and, albeit less prominently than other genetically determines spinocerebellar ataxia, the cerebellum and pons." (PMID 35203288, 2022). "Based on ROC curve analyses, criteria of the measured frataxin were classified and contributed to the diagnostic work-up of four patients who all showed an ataxia phenotype, but who were heterozygous for the GAA repeat expansion." (PMID 26338206, 2015). "Finally, 13/39 sporadic patients with ataxia (33.3%) received a genetic diagnosis as follows: four with homozygous intron 1 expansion in FXN; three biallelic variants in SPG7, 2 CANVAS, 1 SACS, 1 SCA1, 1 SCA2; and one FXTAS." (PMID 33669240, 2021). "Finally, the striking similarity of the symptoms in vitamin E deficiency and frataxin deficiency, both encompassing cerebellar ataxia with inconsistent cardiomyopathy, suggests similar cellular consequences of frataxin and vitamin E depletion." (PMID 21985033, 2011). "FRDA, the most common recessive ataxia, results from a generalized deficiency of mitochondrial and cytosolic iron-sulfur cluster (ISC) proteins activity, due to a partial loss of frataxin function, a mitochondrial protein proposed to function as an iron-chaperone for ISC biosynthesis." (PMID 19703283, 2009). "It is an autosomal recessive neurodegenerative disorder caused by a deficiency of the frataxin (FXN) protein and is the most common inherited ataxia." (PMID 40313117, 2026). "In this study, we present two siblings with neurodevelopmental delay and ataxia, carrying a homozygous pathogenic variant in DNAH14 and pathogenic GAA repeat expansions in the FXN gene in both siblings, confirming a diagnosis of Friedreich’s ataxia (FRDA)." (PMID 41596228, 2026). "Friedreich's ataxia (FA), an autosomal recessive disorder caused in almost all cases by a GAA triplicate expansion in intron 1 of the frataxin (FXN) gene, is characterized as a progressive cerebellar ataxia." (PMID 40017373, 2025). "The autosomal recessive neurodegenerative disease FRDA, characterized mainly by ataxia and degeneration of the spinocerebellar tract, is caused by a GAA expansion in the first intron of the FXN gene." (PMID 32876811, 2020). "The neurodegenerative disease Friedreich's ataxia (FRDA) is the most common autosomal-recessively inherited ataxia and is caused by a GAA triplet repeat expansion in the first intron of the frataxin gene." (PMID 20090835, 2010). "Friedreich's ataxia (FRDA), the most common autosomal recessive ataxia associating spinocerebellar ataxia and cardiomyopathy, is most often due to a (GAA)n repeat expansion within the first intron of the gene encoding the mitochondrial protein frataxin." (PMID 19703283, 2009). "This ataxia is due to a mutation in the frataxin gene (FXN), which is, in most cases, an expansion in a GAA repeat in the first intron leading to a reduced expression of the frataxin protein." (PMID 37628705, 2023).
Ataxia (continued). "This alteration leads to a partial silencing of transcription of frataxin (FXN), its encoded protein, causing a multisystem disorder disease that includes neurological damage, mainly spinocerebellar ataxia, and non-neurological signs such as hypertrophic cardiomyopathy and diabetes Mellitus type 2." (PMID 27941692, 2016). "FXN KO mouse models are embryonically lethal, whereas the inducible hemizygous FXN mice recapitulate hallmarks of FRDA (severe ataxia, mitochondrial and cardiac abnormalities)." (PMID 32876811, 2020). "We studied the adult neuronal growth cone (GC) at the cellular and molecular level to decipher the connection between frataxin and actin cytoskeleton in DRG neurons of the well-characterised YG8R Friedreich’s ataxia mouse model." (PMID 32251310, 2020). "The present work indicates that IGF-I stimulates frataxin levels in a cell-context fashion and is able to restore motor function in a mouse model of FRDA with moderate ataxia." (PMID 23039828, 2012). "As the symptoms worsened rapidly, a novel SACS mutation (c.4003 G>A, p.1335 Val>Ile, Heterozygous) was discovered using WES, although no pathogenic mutations with low frequency were found in ataxia-related genes, such as SPG7, FXN, and GFAP." (PMID 38132465, 2023). "Sustaining a non-cell-autonomous toxic effect of FXN in vivo, the ablation of FXN in astrocytes during development in FGKO mice (where FXN is ablated in a time-dependent manner) caused severe ataxia and early death, inducing growth and survival impairments." (PMID 35682973, 2022). "Mice expressing the full-length human FXN cDNA are normal with no signs of ataxia or other obvious abnormalities; however, these mice have an altered response during hematopoietic differentiation." (PMID 29555919, 2018). "Despite all these limitations, a clear correlation between frataxin levels in whole blood and clinical ataxia severity, as well as age at onset and GAA1 repeat size, could be confirmed, with age at onset being the strongest predictor of frataxin level." (PMID 26338206, 2015). "Abnormalities of the nervous system, including neurodevelopmental abnormality (HP:0012759), ataxia (HP:0001251), seizure (HP:0001250), peripheral neuropathy (HP:0009830) etc., were present in 44% of the families reported, and the top five contributing genes were POLG, SPG7, MFN2, FXN and C19ORF12." (PMID 39423307, 2025). "Collaborative work such as the European Friedreich’s Ataxia Consortium for Translational studies (EFACTS), and the Friedreich’s Ataxia Clinical Outcome Measures (FACOMS) helped evaluate longitudinal changes in clinical assessment tools and develop assays to measure blood frataxin." (PMID 36410013, 2022). "However, as with frataxin depletion, hypersensitivity to oxidative stress has been reported in ABCB7 mutants, suggesting that a common mechanism resulting in impaired handling of reactive oxygen species may be involved at some point in both types of ataxia." (PMID 21985033, 2011). "Since onset of ataxia in FA does not correlate with the degree of neuronal atrophy in DRG, restoration of frataxin can only be expected to preserve residual DRG function." (PMID 27142428, 2016).
cardiomyopathy (40 papers, 2008 to 2025). A disease of the heart muscle or myocardium proper. "In this study, we aimed to characterize a recently developed Fxnflox/null::MCK-Cre mouse model of FA where animals progress rapidly towards severe cardiomyopathy and die prematurely due to FXN loss in the heart." (PMID 39363102, 2024). "Friedreich’s ataxia (FA) is an autosomal recessive disorder caused by reduced frataxin (FXN) expression in mitochondria, where the lethal component is cardiomyopathy." (PMID 39363102, 2024). "Deficiency in the FXN encoded FXN protein leads to a progressive spinocerebellar neurodegeneration associated with gait and limb ataxia, dysarthria, muscle weakness, cardiomyopathy, and diabetes." (PMID 33426505, 2020). "Here, we report for the first time the generation of human engineered tissue models of FRDA cardiomyopathy from hPSCs: FXN-deficient hvCTS displayed attenuated developed forces (by 70–80%) compared to healthy controls." (PMID 31286988, 2019). "The adeno-associated virus 9 (AAV9) has been reported efficiently delivers virus to a conditional mouse model with severe cardiomyopathy caused by complete frataxin deletion in cardiac and skeletal muscle." (PMID 31279523, 2019). "A promising approach toward the replenishment of frataxin in FA patients with cardiomyopathy is the intravenous delivery of an adeno-associated virus vector expressing frataxin." (PMID 25738292, 2015). "Frataxin has been implicated in the mechanism of iron-sulfur cluster biosynthesis; however, the contribution of frataxin-deficiency to cardiomyopathy development has yet to be elucidated." (PMID 26237594, 2014). "Mutations in frataxin result in the development of Friedreich's Ataxia, an inherited neurodegenerative disease associated with the development of severe cardiomyopathy." (PMID 21113085, 2010). "Notably, increased autophagic and apoptotic markers in a cardiac mouse model of FA that exhibit frataxin deficiency implicate their role in the observed cardiomyopathy." (PMID 31057691, 2019). "Collectively, the resulting accumulation of redox active iron, oxidative stress, defective antioxidant response, dysfunction in energy metabolism, and activation of autophagy and apoptosis due to frataxin deficiency leads to the neurodegeneration, ataxia, and cardiomyopathy in FA." (PMID 31057691, 2019). "Thus, there may be a potential association between FXN reduction in the MAMs and mitochondrial dysfunction and cardiomyopathy in DMD." (PMID 38564291, 2024). "To elucidate the molecular mechanisms underlying FRDA-associated cardiomyopathy, we developed a novel isogenic model to study FRDA cardiomyopathy, knocking down frataxin in iCMs post-differentiation." (PMID 36107856, 2023). "To overcome some of these limitations, we developed a novel model to study FRDA cardiomyopathy: we generated isogenic pairs by differentiating wild-type iPSCs into cardiomyocytes and knocking down frataxin post-differentiation." (PMID 36107856, 2023). "A more recent study has utilised a novel isogenic model to investigate FRDA cardiomyopathy, by knocking down frataxin in iPSC-derived isogenic cardiomyocytes post-differentiation." (PMID 37726850, 2023). "A follow-up study utilised FRDA iPSC-derived cardiomyocytes which demonstrated many features characteristic of cardiomyopathy, including a decrease in FXN expression and the pathological accumulation of lipids." (PMID 37726850, 2023). "rhAVV 10-based gene therapy has been successfully achieved in a mouse model of FRDA, and the results showed that the administration of the AAV-frataxin vector was able to completely reverse the cardiomyopathy of mice." (PMID 36359908, 2022). "Gene replacement therapy for FRDA is also under development and has shown initial efficacy in reversing the cardiomyopathy in FXN conditional mutant mice." (PMID 32826895, 2020).
cardiomyopathy (continued). "An in vivo mouse model of skeletal/cardiomyocyte FXN deletion rescued with gene therapy partially prevented and reduced the severity of pre-existing cardiomyopathy." (PMID 33263002, 2020). "We identified four FA cases with patients# 14 and 16 harboring the largest FXN trinucleotide repeat length and showing more severe phenotypes including cardiomyopathy, scoliosis, bladder dysfunction and developmental delay as was previously suggested." (PMID 32999401, 2020). "Our FXN overexpressing mouse model will further help decipher the role of FXN in the development of DOX mediated cardiomyopathy." (PMID 33912028, 2020). "Defective iron sulfur cluster biogenesis due to frataxin deficiency in FRDA leads to mitochondrial iron accumulation by means of still not fully understood mechanisms and is accompanied by progressive cardiomyopathy." (PMID 25878762, 2015). "The authors go on to demonstrate that overexpression of frataxin is cardioprotective against doxorubicin-induced cardiomyopathy." (PMID 21113085, 2010). "Taken together, DOX-induced cardiomyopathy, cardiac function and survival was significantly improved in frataxin-transgenic mice compared to wild-type littermates." (PMID 21084725, 2010). "When AAVrh10 containing hFXN expressed under CAG promoter was intraperitonially injected into MCK-Cre mice, it increased frataxin expression in the heart, leading to preservation of the hemodynamic parameters and cardiac output, and also complete reversal of the cardiomyopathy after disease onset." (PMID 35663795, 2022). "The injection of AAV9-frataxin reverses the functional features of cardiomyopathy." (PMID 31279523, 2019). "Frataxin replacement and anti-inflammatory agents are potential therapies in FA cardiomyopathy." (PMID 25738292, 2015). "The conditional MCK FXN knockout mouse, targeting cardiac and skeletal muscle, develops pronounced cardiomyopathy and significant weight loss, which is likely attributed to the decrease in lean mass due to cardiomyopathy/skeletal muscle dysfunction rather than a decrease in fat mass." (PMID 37701569, 2023). "For instance, they should be exhibiting a progression of sensory ataxia and/or cardiomyopathy due to reduced frataxin protein level, ideally as a result of GAA expansions in the first intron of the FXN gene." (PMID 36036008, 2022). "Both the YG8-800 and KIKO-700 mouse models have more than 20% FXN in the heart, likely explaining the lack of alterations of cardiomyopathy and stress markers." (PMID 37691621, 2023). "The dramatic decrease (<1% residual FXN), however, did not result in a fatal cardiomyopathy, at least up to 18 months, unlike the cKO model, nor did it cause ACO and SDH enzymatic defects." (PMID 37691621, 2023). "In summary, our findings indicate that FXN plays a significant role in the development of DOX mediated myocardial iron overload and that PAESe protects FXN from the impaired mitochondrial bioenergetics leading to progression of de-compensatory cardiomyopathy." (PMID 33912028, 2020). "There were no significant gender differences in disease duration, SARA score, age at onset, cardiomyopathy, scoliosis, depression, frataxin level nor GAA repeat lengths." (PMID 26338206, 2015). "The frataxin fusion protein (TAT-FXN) was delivered to different tissues, including heart, DRG, and cerebellum, and to the mitochondria, boosting respiratory chain activity and positively increasing the life span of the conditional heart model with a partial recovery of cardiomyopathy." (PMID 38391932, 2024). "By contrast, recently developed FA models such as UCLA and YG8-800 mice, featuring inducible FXN knockdown and larger triplets’ expansion, exhibit early onset, severe neurodegeneration, and cardiomyopathy, but do not report T2D-like signs and experience weight loss." (PMID 37701569, 2023).
cardiomyopathy (continued). "FXN is an essential mitochondrial protein and the resultant FXN insufficiency results in progressive spinocerebellar neurodegeneration and cardiomyopathy, leading to a progressive lack of motor coordination, incapacity and eventually death, usually in early adulthood." (PMID 22973455, 2012). "However, treatment of cardiac/skeletal muscle FXN-knockout mice with NAC actually decreases Nrf2 levels and proves no benefit in development of cardiomyopathy." (PMID 33263002, 2020).
diabetes (20 papers, 2010 to 2025). "Loss of FXN is a susceptibility factor in the development of diabetes, a common metabolic complication after myocardial hypertrophy in patients with FRDA." (PMID 39191875, 2024). "It has been reported that FXN deficiency is a high risk factor in diabetes in FRDA patients and mice, and DPN is the most common complication of diabetes." (PMID 39334695, 2024). "Furthermore, YG8R mice exhibited very mild, without significance, changes in insulin sensitivity compared with Y47 mice at 16 weeks of age, suggesting a late diabetes manifestation under FXN-deficient conditions." (PMID 39191875, 2024). "Interestingly, disruption of the frataxin gene in mice causes the loss of β-cell mass and then diabetes." (PMID 33198243, 2020). "Similarly, targeted disruption of frataxin, a mitochondrial iron-binding protein in pancreatic β-cell, causes increased islet ROS, decreased islet mass, and diabetes in mice." (PMID 26613076, 2015). "Furthermore, patients with mutations in the frataxin gene develop diabetes in 23% of cases." (PMID 26613076, 2015). "FXN deficiency primarily impairs WAT lipolysis from the young age, far earlier than insulin-resistance manifestation, and aggravates diet-induced diabetes and insulin resistance." (PMID 39191875, 2024). "The upregulation of MKNK1, Frataxin (FRDA), and electron transfer flavoprotein-ubiquinone oxidoreductase (ETFD) can help decrease the risk of diabetes mellitus." (PMID 36982812, 2023). "FXN downregulation in cultured adipocytes mirrored vWAT diabetes-like features, showing metabolic shifts toward glycolysis and lactate production." (PMID 37701569, 2023). "We previously demonstrated that expression of frataxin correlates with mitochondrial energy metabolism in vitro and in vivo, affecting processes as diverse as longevity, diabetes, as well as growth and formation of cancer cells." (PMID 21084725, 2010). "Manipulation of their expression correlates well with DPN symptoms, suggesting that hyperglycemia in patients with diabetes might reduce FXN and ISCU expression to compromise mitochondrial function, contributing to the development of DPN." (PMID 39334695, 2024). "If clinical data support our findings, diabetes patients with DPN might consider being prescribed PGZ to reverse the expression of FXN and ISCU to alleviate axon degeneration in addition to the first-line drug metformin." (PMID 39334695, 2024). "Our results revealed the interaction of FXN and PPARγ signaling pathway, shedding light on a pharmaceutical strategy for a positive feedback development in treating FRDA, beneficial from both diabetes and neurodegeneration." (PMID 39191875, 2024). "There are 146 recommendations related to 1) the neurological components of FRDA; 2) the heart, cardiovascular and respiratory system; 3) scoliosis; 4) diabetes mellitus; 5) genetic issues; 6) FRDA due to FXN compound heterozygosity; 7) pregnancy issues; 8) quality of life issues." (PMID 25928624, 2014).
hereditary ataxia (14 papers, 2011 to 2026). An instance of an atactic disorder that is caused by an inherited genomic modification in an individual. "Friedrich’s ataxia (FA), the most common form of hereditary ataxia, is a genetic disorder caused by a mutation in the frataxin (FXN) gene, resulting in intra-mitochondrial iron accumulation, reactive oxygen species production, and abnormalities of oxidative phosphorylation." (PMID 39969761, 2025). "Friedreich's ataxia (FRDA) is the most common early onset hereditary ataxia, caused by GAA repeat expansions in the FXN gene." (PMID 41954755, 2026). "In patients with suspected hereditary ataxia, we identified expansions in loci that had not been assessed as part of routine diagnostic workup within the NHS at the time of recruitment, including ATN1, ATXN2, ATXN3, ATXN7, CACNA1A, FXN, TBP, and HTT." (PMID 35182509, 2022).